ADGRD1 (adhesion G protein-coupled receptor D1)
Description:
Adhesion G protein-coupled receptor (aGPCR) for androgen hormone 5alpha-dihydrotestosterone (5alpha-DHT), also named 17beta-hydroxy-5alpha-androstan-3-one, the most potent hormone among androgens. Also activated by methenolone drug. Ligand binding causes a conformation change that triggers signaling via guanine nucleotide-binding proteins (G proteins) and modulates the activity of downstream effectors, such as adenylate cyclase. ADGRD1 is coupled to G(s) G proteins and mediates activation of adenylate cyclase activity. Acts as a 5alpha-DHT receptor in muscle cells, thereby increasing intracellular cyclic AMP (cAMP) levels and enhancing muscle strength.
Synonyms: GPR133; PGR25; DKFZp434B1272
Tractability: Small molecule: a structure with a bound ligand is known. Antibody: UniProt places it where antibodies can reach, with high confidence; its Gene Ontology location is reachable by antibodies, with high confidence; UniProt predicts a signal peptide or a membrane-spanning region.
Target class: Family B G protein-coupled receptor; Membrane receptor
Gene: Protein-coding gene on chromosome 12 (130,953,055 to 131,142,466, forward strand). Ensembl gene ENSG00000111452.
Subcellular location: Cell membrane
Subcellular location (Human Protein Atlas): Plasma membrane; Nuclear speckles; Nucleoplasm
Gene Ontology:
Molecular function: G protein-coupled receptor activity; protein binding; transmembrane signaling receptor activity
Biological process: adenylate cyclase-activating G protein-coupled receptor signaling pathway; G protein-coupled receptor signaling pathway; regulation of skeletal muscle contraction; cell surface receptor signaling pathway
Cellular component: plasma membrane; membrane
Genetic constraint (gnomAD): Loss-of-function variants: 54 observed, 82.02 expected, observed/expected ratio (o/e) 0.66, 90% interval 0.53 to 0.83. The upper end of that interval is the gene's LOEUF score, 0.83, which puts it in group 3 of 6, group 1 being the genes least tolerant of losing a copy. Missense variants: 884 observed, 980.38 expected, observed/expected ratio (o/e) 0.9, 90% interval 0.85 to 0.95. Synonymous variants: 413 observed, 415.38 expected, observed/expected ratio (o/e) 0.99, 90% interval 0.92 to 1.08.
Homologues: Orthologues: chimpanzee ADGRD1 (95% identical), macaque ADGRD1 (92% identical), pig ADGRD1 (82% identical), mouse Adgrd1 (81% identical), rat Adgrd1 (80% identical), dog ADGRD1 (78% identical), rabbit ADGRD1 (76% identical), guinea pig ADGRD1 (76% identical), tropical clawed frog adgrd1 (61% identical), zebrafish adgrd1 (30% identical). Paralogues in human: ADGRL3 (23% identical), ADGRL2 (22% identical), ADGRL1 (22% identical), ADGRF5 (20% identical), ADGRE2 (20% identical), ADGRE1 (19% identical), ADGRE5 (19% identical), ADGRB3 (19% identical), ADGRL4 (19% identical), ADGRB2 (18% identical), ADGRG4 (18% identical), ADGRB1 (18% identical), and 30 more.
Diseases named in the same sentence as ADGRD1 in open-access papers:
ADGRD1 is named in the same sentence as 52 diseases in open-access papers, as found by Europe PMC text mining. Sharing a sentence is not in itself a finding about the gene and the disease. The quoted sentences say what the papers report.
glioblastoma (12 papers, 2016 to 2025). The most malignant astrocytic tumor (WHO grade IV). "ADGRD1/GPR133 has been implicated as a critical regulator of the response to hypoxia and tumour growth in glioblastoma." (PMID 38786015, 2024). "For instance, ADGRD1 (gpr133) is highly expressed in glioblastoma and plays a role in tumor progression." (PMID 41614755, 2025). "We previously demonstrated that the adhesion G protein-coupled receptor GPR133 (ADGRD1) is necessary for tumor growth in adult glioblastoma, the most advanced malignancy within the glioma family." (PMID 32642706, 2020). "Our group recently demonstrated part of the mechanism that mediates the activation of GPR133 (ADGRD1), a member of group V of aGPCRs implicated in the pathogenesis of glioblastoma (GBM), an aggressive brain malignancy." (PMID 35447113, 2022). "We recently demonstrated that GPR133 (ADGRD1), an adhesion G protein–coupled receptor involved in raising cytosolic cAMP levels, is necessary for growth of glioblastoma (GBM) and is de novo expressed in GBM relative to normal brain tissue." (PMID 35447113, 2022). "GPR133 (ADGRD1), an adhesion G protein–coupled receptor (GPCR) whose canonical signaling activates GαS-mediated generation of cytosolic cAMP, has been shown to be necessary for the growth of glioblastoma (GBM), a brain malignancy." (PMID 34022221, 2021). "However, various aGPCRs have been associated with cancer development and progression including GPR133/ADGRD1, which is required for glioblastoma growth; GPR116/ADGRF5, which furthers breast cancer metastasis; and CD97/ADGRE5 seems to enhance tumor cell invasion in several human malignancies." (PMID 29594040, 2018).
glioma (3 papers, 2020 to 2025). A benign or malignant brain and spinal cord tumor that arises from glial cells (astrocytes, oligodendrocytes, ependymal cells). "Necrotic and pseudopalisading zones within GBM promote the expression of GPR133 (ADGRD1), a member of the adhesion G protein–coupled receptor (AGPCR) family, specifically in CD133+ glioma stem cells." (PMID 41155273, 2025).
breast carcinoma (2 papers, 2018 to 2025). "We repositioned progesterone to ADGRD1 for pemphigus and breast cancer, as well as estradiol to ANO2 for shingles and medulloblastoma, which were validated via molecular docking." (PMID 39860130, 2025).
cardiomyopathies (1 paper, 2023). "ADGRD1 and BST2 have not been previously associated with cardiomyopathies and/or heart failure and represent targets for elucidating pathophysiological mechanisms and future drug development." (PMID 36950336, 2023).
infertile (1 paper, 2021). "Together, these results show that the postovulatory cessation of oviductal fluid flow is misregulated in the oviduct of Adgrd1-deficient mice which could prevent embryo passage of the AIJ and cause infertility." (PMID 33623007, 2021). "Here, the authors show that female mice lacking the adhesion G-protein coupled receptor Adgrd1 are infertile, due to embryos being trapped in the ampulla as the result of dysregulated oviductal fluid flow." (PMID 33623007, 2021).
liver fibrosis (1 paper, 2025). "Wt1+ fibroblasts displayed distinct expression of genes, such as Scara5, Fbln2, Adgrd1, and Osr1 (encoding the odd-skipped related transcription factor 1) that has been linked to liver fibrosis, and mesenchymal collagen production (Fig. EV3E)." (PMID 40954217, 2025).
mesothelioma (1 paper, 2022). A usually malignant and aggressive neoplasm of the mesothelium which is often associated with exposure to asbestos. "The results showed that ADGRD1 played an important role in the prognosis of twelve cancers, which included adrenocortical carcinoma (ACC), COAD, KIRP, LAML, brain lower grade glioma (LGG), liver hepatocellular carcinoma (LIHC), LUAD, LUSC, mesothelioma (MESO), READ, sarcoma (SARC), and STAD." (PMID 36457341, 2022).
Osteopenia (1 paper, 2025). Osteopenia is a term to define bone density that is not normal but also not as low as osteoporosis. "Intermittent application of the novel GPR133/ADGRD1 agonist AP503 successfully rescued osteopenia in heterozygous mice and increased bone formation and strength in WT animals." (PMID 40583059, 2025).
osteoporosis (1 paper, 2025). A condition of reduced bone mass, with decreased cortical thickness and a decrease in the number and size of the trabeculae of cancellous bone (but normal chemical composition), resulting in increased fracture incidence. "Given that heterozygous KO mice exhibited intermediate phenotypes with several indicators of osteoporosis, variants in Gpr133/Adgrd1 could represent a genetic risk factor in humans." (PMID 40583059, 2025). "Constitutive and osteoblast-specific knockouts of Gpr133/Adgrd1 in mice lead to reduced cortical bone mass and trabecularization in the femurs and vertebrae — features characteristic of osteoporosis." (PMID 40583059, 2025). "The recently developed GPR133/ADGRD1 agonist AP50320 induces osteoblastogenesis in vitro and in vivo and significantly alleviates osteoporosis in vivo in an ovariectomy mouse model." (PMID 40583059, 2025). "Activation of GPR133/ADGRD1 with the receptor-specific ligand AP-970/43482503 (AP503) enhances osteoblast function and differentiation, both in vitro and in vivo, significantly alleviating osteoporosis in a mouse ovariectomy model." (PMID 40583059, 2025).
viral infections (1 paper, 2024). "In light of reanalysed RNAseq data and our findings, we believe that further research into the role of ADGRD1/GPR133 (but likely not ADGRG7/GPR128) in viral infections is warranted." (PMID 38786015, 2024).
tumor (14 papers, 2016 to 2026). "We explore the association between tumor immune microenvironment, immune infiltrating cells, and ADGRD1 expression." (PMID 36457341, 2022). "Third, despite the expression of ADGRD1 was detected to be associated with tumor-infiltrating immune cells and prognosis of patients, we were unable to confirm the exact mechanism of the prognostic features." (PMID 36457341, 2022). "The findings suggested that abnormal ADGRD1 expression could be a useful biomarker for tumor detection and treatment and linked to MSI and TMB." (PMID 36457341, 2022). "By modulating the PI3K/AKT/mTOR signaling axis and the pro-angiogenic microenvironment, ADGRD1 facilitates tumor growth and neovascularization." (PMID 42294320, 2026). "Tumor stage and the ADGRD1, ADGRE3, and LGR4 genes were identified to be independently associated with the prognosis of patients with LUAD." (PMID 40364562, 2025). "Meanwhile, the data was also used to evaluate ADGRD1 expression in 33 tumor tissues, and the expression level of gene ADGRD1 in LUAD and LUSC was ranked third and thirteenth, respectively." (PMID 36457341, 2022). "In NSCLC, ADGRD1 expression was lowered and significantly associated with prognosis, TMB, MSI, tumor microenvironment, and immune infiltrating cells." (PMID 36457341, 2022). "However, there have been few reports linking ADGRD1 to the tumor microenvironment." (PMID 36457341, 2022). "Functional assays demonstrated that ADGRD1 promotes BLCA cell proliferation, migration, invasion, and endothelial tube formation in vitro, and enhances tumor growth and angiogenesis in vivo." (PMID 42294320, 2026). "In both TCGA‐LUAD, in the GSE30219 and GSE18842 cohorts, the expression of ADRB1, ADGRD1, and ADGRE3 were reduced, whereas the expression of OR51E1 and LGR4 were elevated in tumor samples." (PMID 40364562, 2025). "In this research, we investigated the underlying molecular mechanism of ADGRD1 across cancers; downregulation of ADGRD1 expression in NSCLC was significantly correlated with prognosis, TMB, MSI, tumor microenvironment, and immune infiltrating cells." (PMID 36457341, 2022). "Here, we use primary human tumor biospecimens and cultures to identify GPR133 (ADGRD1), an orphan member of the adhesion family of G-protein-coupled receptors, as a critical regulator of the response to hypoxia and tumor growth in GBM." (PMID 27775701, 2016).
cancer (5 papers, 2016 to 2023). A tumor composed of atypical neoplastic, often pleomorphic cells that invade other tissues. "ADGRD1, an adhesion G protein-coupled receptor, is a key modulator of signal transduction and has been linked to cancer." (PMID 36457341, 2022). "In addition, Adhesion G Protein-Coupled Receptor G1 (ADGRD1) functions in cell matrix adhesion and cancer progression [reviewed in 52], and KITLG (SCF/c-Kit) encodes the cytokine that acts as the ligand for the tyrosine-kinase KIT receptor." (PMID 37276213, 2023). "According to our pan-cancer analysis, ADGRD1 had a critical effect on prognosis of different cancers." (PMID 36457341, 2022). "Multiple databases were used in this study for exploring the prognostic significance of ADGRD1 within pan-cancer." (PMID 36457341, 2022). "In the analysis of the association between ADGRD1 expression and TMB, MSI in pan-cancer is essential." (PMID 36457341, 2022). "This provides new ideas and directions for strengthening the understanding of ADGRD1 in various cancers and revealing it as a new clinical biomarker for prognosis and immunotherapy." (PMID 36457341, 2022). "ADGRD1 (GPR133), an adhesion G protein-coupled receptor (GPCR), has been linked to cancer." (PMID 36457341, 2022). "It has also been suggested that LINC02407 is closely related to CASC19 and cancer cell survival and affects GC via the LINC02407-miR-6845-5p/miR-4455/ADGRD1 pathway." (PMID 36928327, 2023). "According to this study, ADGRD1 expression is related to TMB in 16 cancer types, including LUAD and LUSC, and MSI in 6 cancer types, including LUSC." (PMID 36457341, 2022). "First, we used the Cox regression to analyze the impact of ADGRD1 expression among OS, DSS, DFI, and PFI in pan-cancer." (PMID 36457341, 2022). "Previously, biological function of ADGRD1 in different human cancers has not been completely explored and only a few researches on ADGRD1 analysis in NSCLC have been published." (PMID 36457341, 2022). "Furthermore, we calculated the correlation between ADGRD1 expression and MSI across cancers." (PMID 36457341, 2022).
bone disorder (1 paper, 2025). "Given that the GPCR class is among the most widely used molecular targets for therapeutics approved by the U.S. Food and Drug Administration, GPR133/ADGRD1 could serve as a new drug target for treating bone disorders." (PMID 40583059, 2025).
infection (1 paper, 2024). The state of being infected such as from the introduction of a foreign agent such as serum, vaccine, antigenic substance or organism. "In Calu-3 cells, the relative mRNA expression upon infection with infectious SARS-CoV-2 exhibited a pronounced increase in the cases of ADGRD1/GPR133 and ADGRG7/GPR128, a small increase in the case of ADGRB3/BAI3 and a negligible change in that of ADGRV1/GPR98 mRNA levels after 24 and 48 h." (PMID 38786015, 2024). "The increase in mRNA expression of ADGRD1/GPR133 and ADGRG7/GPR128 after 24/48 h increased more than three times compared to the mRNA expression change 12 h after infection." (PMID 38786015, 2024). "It is worthy of note that the increase in mRNA expression of ADGRD1/GPR133 observed 12 h after infection was not sustained after 24 or 48 h." (PMID 38786015, 2024).
ADGRD1 also shares sentences with these, for which no sentence is quoted: lung adenocarcinoma (3 papers); non-small cell lung carcinoma (2); acute myeloid leukemia (1); astrocytic tumor (1); astrocytomas (1); atopic dermatitis (1); autonomic dysfunction (1); bladder cancer (1); Brachycephaly (1); brain disorder (1); cervical squamous cell carcinoma (1); congenital heart defects (1); cortical dysplasia (1); endocervical adenocarcinoma (1); endometriosis (1); escherichia coli infection (1); gastric cancer (1); gastrointestinal stromal tumor (1); heart failure (1); lung squamous cell carcinoma (1); medulloblastoma (1); Miscarriage (1); myocardial infarction (1); neurodevelopmental disorder (1); neurological disease (1); oligodendroglial tumor (1); oligodendroglioma (1); oral squamous cell carcinoma (1); ovarian serous cystadenocarcinoma (1); Pan (1).
A further 8 diseases each share a sentence with ADGRD1 in 1 paper.